EPO (erythropoietin)
Diseases named in the same sentence as EPO in open-access papers (continued):
Sharing a sentence is not in itself a finding about the gene and the disease.
anemia (continued). "HIF-PHIs are available as oral agents whose primary mechanism of action is to promote endogenous EPO production, and the continuous administration of HIF-PHIs improves anemia at physiological EPO blood concentrations." (PMID 36769359, 2023). "Comparatively, on the other hand, NDD-CKD patients with anemia had lower eGFR but were older, had more diabetes, and had higher sFas/ eGFR, EPO/Hb ratios, and serum levels of IL-6 and sFas than NDD-CKD without anemia for an extended period." (PMID 37390095, 2023). "Currently, there is no consensus regarding reference gene selection for RT-qPCR analysis of neonatal rat retina tissue across the experimental conditions of OIR, anemia, its treatment with recombinant human erythropoietin (EPO) and room air control (RA)." (PMID 37098032, 2023). "In the case of chemotherapy-induced anemia, EPO usually starts at 40,000 units per week and can be increased up to 60,000 units per week." (PMID 38029231, 2023). "The most common adverse event for HIF-2α inhibitors is likely anemia because erythropoietin (EPO), which stimulates red blood cell production, is driven by HIF-2α expression." (PMID 37124241, 2023). "Other researchers previously reported that hyperglycemia determines hypoxic stress in the kidney interstitium, impairing erythropoietin production, and anemia in diabetes aggravates diabetic kidney disease and cardiovascular disease." (PMID 37390095, 2023). "In a study by Gruber M, both newborn and adult rats with EPAS1 knockout presented with anemia or severe pancytopenia with suppressed EPO production, indicating the pro-erythrocytosis effect of HIF-2α by transcriptionally regulating EPO production." (PMID 36923253, 2023). "Recombinant human erythropoietin (rhEPO) treatment is an alternative to red blood cell (RBC) transfusions in neonates presenting anemia of prematurity (AOP)." (PMID 38136044, 2023). "Treatment of anemia aims at replacing the endogenous EPO feedback through recurrent administrations of erythropoiesis-stimulating agents (ESAs) such as recombinant human erythropoietin (rHuEPO)." (PMID 36693034, 2023). "Rarely, allergic reactions to recombinant human erythropoietin can develop, complicating anemia management due to cross-reactivity between these agents." (PMID 37456430, 2023). "Erythropoietin (EPO) is a U.S. Food and Drug Administration (FDA) approved drug for the treatment of anemia associated with chronic kidney disease." (PMID 37127673, 2023). "The important association of erythropoietin (EPO) serum levels and chronic obstructive pulmonary disease (COPD) with anemia has been inadequately studied and remains a controversial issue." (PMID 37117600, 2023). "Anaemia in CKD often has more than one cause, including lower erythropoietin (EPO) levels, inflammation, bleeding and reduced iron availability all resulting in a reduced number of healthy circulating erythrocytes." (PMID 36048866, 2023). "In reaction to hypoxia or anemia, renal hypoxia raises EPO synthesis and circulating levels, positively driving erythropoiesis." (PMID 38022248, 2023). "Treatment for anaemia among patients with CKD has focused on administering erythropoietin-stimulating agents (ESAs) and iron supplementation." (PMID 37623232, 2023). "The reduction in HCT, along with severity of CKD was mainly due to the failure to produce EPO relative to the severity of anemia." (PMID 36855344, 2023). "Anemia is typically treated using drugs that mimic erythropoietin, the body’s own hormone regulating red blood cell generation in healthy subjects." (PMID 36693034, 2023). "Although erythropoietin-stimulating agents (ESAs) are available, the management of anemia in patients who receive renal replacement therapy is controversial." (PMID 37391687, 2023). "Chronic kidney disease (CKD) involves a gradual decrease of kidney function, which led to low EPO levels as well as RBC deficiency and development of anemia." (PMID 37919778, 2023).
anemia (continued). "EPO and erythropoiesis-stimulating agents (ESAs) have been used to manage chemotherapy-induced anemia in cancer patients." (PMID 37543610, 2023). "In this study, 26 patients with severe heart failure and anemia were treated with a combination of erythropoietin and intravenous iron therapy to improve anemia." (PMID 36983057, 2023). "Renal transplant aims to provide a healthy substitute for the chronically damaged kidney while also correcting the anemia of chronic disease by producing erythropoietin for effective erythropoiesis." (PMID 38283474, 2023). "EPO production also didn’t compensate for the anemia of chronic disease which considers as a common comorbid disorder in these patients." (PMID 37117600, 2023). "Therapy was based on controlling inflammation with the use of glucocorticoids and treating MDS-related anemia with the use of erythropoietin." (PMID 38206689, 2023). "The decision to test EPO levels in anemia patients was solely based on the treating physician's choice, as there were no specific predefined criteria for such testing in our center." (PMID 37741889, 2023). "Anemia of chronic disease, which is observed in TB, results from inflammation-related factors affecting the erythrocyte lifespan, iron incorporation, and erythropoietin sensitivity." (PMID 38201359, 2023). "Anemia in CKD is multifactorial in etiology, but the most widely accepted cause is decreased erythropoietin production by the kidney." (PMID 38021836, 2023). "Recombinant human erythropoietin, ESA, or erythropoietin analogs were introduced in 1989, a milestone in treating anemia in CKD patients." (PMID 37602095, 2023). "The decrease in endogenous erythropoietin together with the anemia-related reduced oxygen transport aggravates tissue hypoxia and neurohormonal overactivity, facilitating the further deterioration of renal and cardiac function." (PMID 37763045, 2023). "Androgens were the only way to treat men with chronic kidney disease anemia before the advent of EPO." (PMID 36797683, 2023). "Impaired erythropoiesis also contributes to anemia due to poor response to EPO with reduced proliferative activity of erythroid precursors in bone marrow and erythrophagocytosis." (PMID 35937691, 2022). "Anemia in ESRD is most often attributed to decreased relative erythropoietin (EPO) secretion from the kidney." (PMID 35846199, 2022). "It was found that EPO-R-deficient mice develop severe anemia and impaired EPC function, making the role of EPO in erythropoiesis crucial." (PMID 36567722, 2022). "Clinically, recombinant human EPO (rHuEPO) is widely used to treat anemia in patients with advanced chronic kidney disease or that induced by cancer and chemotherapy, particularly in cases of multiple myeloma (MM) and myelodysplastic syndromes (MDS)." (PMID 36233351, 2022). "Erythropoietin (EPO) is a pleiotropic hormone produced mainly by the adult kidney in response to hypoxia or anemia to increase the production of red blood cells." (PMID 35659624, 2022). "These impairments and aberrations lead to muscle cramps, dialysis-related hypotension, myopathy, cardiomyopathy, and erythropoietin-resistant anemia among hemodialysis patients." (PMID 35834513, 2022). "Previously, some authors have proved that total MIS score correlates inversely with the severity of anemia and, on the other hand, is positively correlated with total weekly weight-adjusted dose of EPO." (PMID 35566552, 2022). "For our work, an AAN model of erythropoietin therapy for patients with the anemia of CKD was developed incorporating the target hemoglobin, erythropoietin type, maximum dosage, as well as other factors the physician would take into consideration." (PMID 35402468, 2022). "The rhGH group less frequently received treatment with erythropoietin, and less frequently showed anemia which was most pronounced during late post-transplant years (p < 0.05)." (PMID 34542703, 2022).
anemia (continued). "The standard treatment for anemia of CKD includes the use of recombinant human erythropoietin (rhEPO) and its analogs to increase hemoglobin levels." (PMID 35355447, 2022). "As kidney disease progresses, the kidneys are unable to produce sufficient amount of EPO and the prevalence of anemia increases, affecting nearly all patients with stage 5 CKD / end stage renal disease (ESRD)." (PMID 35813388, 2022). "PHIs are specific drugs that activate HPHE signaling and were developed to stimulate the production of endogenous EPO in anemia of CKD." (PMID 35445830, 2022). "HIF activation promotes erythropoietin transcription in both the kidney and liver to alleviate anemia." (PMID 35620283, 2022). "Synthetic EPO has been successfully used to correct anemia for patients with ESRD since the first use in 1987." (PMID 36077032, 2022). "Examples of promising HIF-hydroxylase inhibitors are GKS-1278863, FG-4592, and AKB-6548, all of which increase circulating erythropoietin and help to alleviate anemia in these patients [reviewed by Haase (2017)]." (PMID 35755436, 2022). "Anemia is a common complication in CKD, particularly in the latter stages, and the main cause is an inadequate production of erythropoietin by the failing kidneys." (PMID 36289903, 2022). "Substitution therapy of iron and erythropoietin in the context of anemia of chronic disease also changes the course of blood values compared to a patient in whom this substitution does not take place." (PMID 35574347, 2022). "The sustained anemia and elevated erythropoietin levels stimulate erythroid precursors to release erythroferrone, which suppresses hepcidin expression, the main regulator of intestinal iron absorption in the body." (PMID 36295656, 2022). "EPO belongs to the class I cytokine family and is well studied and widely prescribed for the treatment of anemia." (PMID 36081576, 2022). "Anemia is a common complication of CKD that develops primarily due to insufficient secretion of EPO by the diseased kidneys." (PMID 35813388, 2022). "Roxadustat, the first small-molecule PHI, can lead to increased EPO production, better iron absorption, and amelioration of anemia in CKD." (PMID 36364144, 2022). "Lactoferrin was administered as two tablets daily (equivalent to 200 mg daily), along with recombinant human erythropoietin, to people with anemia." (PMID 35807823, 2022). "A principal reason that the hemoglobin concentration is lower in preterm than in full-term newborns is the decreased plasma erythropoietin (EPO) level in response to anemia." (PMID 35740728, 2022). "Current understanding of space anemia is that the decrease in RBCs constitutes an acute adaptation to major hemodynamic events of cephalad fluid shifts, hemoconcentration and low erythropoietin (EPO) levels upon entering microgravity." (PMID 35031790, 2022). "Another known erythroid regulator is erythropoietin (EPO), which comes into play when there is a need for an enhanced erythropoiesis, such as during anemia or hypoxia, leading to a decrease in hepcidin to allow increased iron release and mobilization." (PMID 35464433, 2022). "Usually, ESKD patients suffer from anemia as a consequence of decreased production of erythropoietin (EPO) by damaged kidneys." (PMID 36303122, 2022). "The oral hypoxia-inducible factor (HIF) prolyl hydroxylase inhibitors are potential alternatives to the ESA (erythropoietin-stimulating agents) approach for the treatment of anemia in patients with CKD." (PMID 36142323, 2022). "FGF23 is a negative regulator of bone metabolism and PTH secretion, mainly produced by bone and erythroid cells in response to the anemia-related factor EPO." (PMID 35631417, 2022). "Insufficient production of erythropoietin (EPO) is one of the most important pathological mechanisms leading to anemia in CKD patients." (PMID 36364144, 2022).
anemia (continued). "Although erythropoietin-stimulating agents are effective in treating anemia in patients with end-stage kidney disease (ESKD) undergoing hemodialysis, some ESKD patients, especially those with inflammation, continue to suffer from anemia." (PMID 35887674, 2022). "EPO, mainly used for treating anemia clinically, has protective effects on multiple organs and prevents tissue injury during inflammation and ischemia." (PMID 35656290, 2022). "Patient 2 (85 years old woman) experienced grade 2 anemia, requiring blood transfusions and erythropoietin injection during and after the third cycle of PRRT, due to poor tolerance." (PMID 36005176, 2022). "In mice with iron deficiency anemia (IDA), decreased hematologic parameters were accompanied by pronounced decreases in serum and tissue iron concentrations, and an increase in serum erythropoietin." (PMID 35634155, 2022). "Under conditions of anemia and hypoxia, erythropoietin (EPO) production is markedly activated in the kidneys to compensate for RBC hemolysis leading to bone marrow expansion, skeletal changes, and hepatosplenomegaly." (PMID 36620219, 2022). "In 1986, recombinant human EPO (rhEPO) was used to treat patients with end-stage renal failure and anemia, elevating the hemoglobin concentration of the plasma in 9 out of 12 patients." (PMID 35250554, 2022). "The most common treatment options for cancer-related anemia include iron supplements, red cell transfusion, and erythropoietic-stimulating agents (ESAs) including erythropoietin (EPO) and its analogs." (PMID 36518596, 2022). "For 4 decades, millions of patients have received erythropoietin (EPO) as front-line therapy for several types of anemia, improving their prognoses and quality of life." (PMID 35847006, 2022). "It has been observed that inflammatory mediators inhibited erythroid cell differentiation, shortened erythrocyte half-life, and suppressed erythropoietin response to anemia, resulting in anemia of inflammation." (PMID 36297019, 2022). "Concurrent cardiorespiratory and infectious illnesses, the need for bloodwork, and developmentally regulated physiologic processes (i.e., decreased erythropoietin production, shorter lifespan of fetal erythrocytes) contribute to progressive anemia." (PMID 36558502, 2022). "This study shows that during anemia a similar mechanism is present in teleost fish, with increases in erythropoietin expression in the spleen and head kidney, as well as an increase in erythroferrone expression and hepcidin suppression." (PMID 35464433, 2022). "This is the first randomized clinical trial that assesses the role of erythropoietin treatment in hospitalized patients with acute kidney injury and anemia." (PMID 35279078, 2022). "Recently, we detected autoantibodies to EPOR that can induce anemia by inhibiting EPO–EPOR interaction on erythroid progenitor cells." (PMID 36140193, 2022). "Erythropoietin infusions or other erythropoietin-stimulating agents manage anaemia in end-stage renal disease patients." (PMID 36263390, 2022). "Anemia is usually accompanied by a regulatory increase in endogenous EPO production due to hypoxia-mediated feedback mechanisms." (PMID 36211426, 2022). "It has been observed in mice that during anemia or after pharmacological inhibition of PHDs a subpopulation of interstitial cells coexpresses EPO and renin suggesting an endocrine plasticity of these cells." (PMID 35511367, 2022). "A combination of genetic and functional studies provides a powerful approach to investigate the potential therapeutic profile of EPO-increasing therapies for treating anemia in CKD." (PMID 36055212, 2022). "Patients with chronic kidney disease (CKD) develop anemia largely because of inappropriately low erythropoietin (EPO) production and insufficient iron available to erythroid precursors." (PMID 35751858, 2022). "CKD-based anemia primarily results from reduced EPO production and the generation of a blunted response from the erythroid progenitors toward EPO." (PMID 36349057, 2022).
anemia (continued). "Accordingly, anemia in patients with advanced CKD was targeted with EPO or erythropoiesis-stimulating agents (ESAs), along with oral or intravenous iron supplementation." (PMID 35222025, 2022). "In Burkina Faso, red blood cell (RBC) transfusion remains the crucial anaemia treatment following chronic renal failure (CRF) as erythropoietin and its analogues are unavailable." (PMID 36263390, 2022). "The anemia will lead to increased erythropoietin levels to compensate for the tissue hypoxia, which consequently stimulates the Janus kinase 2 (JAK2)-dependent phosphorylation cascade." (PMID 36295656, 2022). "Anemia is a common complication in patients with advanced chronic kidney disease (CKD), involving multiple mechanisms including relative erythropoietin deficiency and impaired iron absorption and utilization." (PMID 35355447, 2022). "Second, we applied different mouse models with high RDW induced by anemia, transplanted colon cancer cells, erythropoietin treatment or thalassemia." (PMID 35953533, 2022). "EPO analogues and iron replacement are the current treatments for anemia, but the Food and Drug Administration (FDA) has issued a warning for the usage of EPO analogues because their usage results in a greater risk of serious side effects." (PMID 36324690, 2022). "Acute correction of anemia with EPO and new agents that increase endogenous EPO production, the hypoxia‐inducible factor‐prolylhydroxylase inhibitors (HIF‐PHI), have been shown to fully rescue complete blood counts in the adenine‐CKD model." (PMID 35656701, 2022). "One mechanism describes that the increased erythropoietin (EPO) levels in anemia can induce a positive stimulation of thrombopoiesis." (PMID 35711252, 2022). "Neonates < 32 weeks’ gestation are at higher risk of abrupt postnatal decrease in hemoglobin levels along with inappropriately low reticulocyte count and circulating erythropoietin concentration for the degree of anemia." (PMID 36558502, 2022). "In response to anemia and hypoxia, EPO, which is a glycoprotein hormone, plays an important role in increasing the production of red blood cells, and EPO is produced in adult kidney and fetal liver." (PMID 35677638, 2022). "As a renal hormone regulating hematopoiesis, erythropoietin (EPO) is initially applied for anemia recovery." (PMID 36176612, 2022). "The lack of acetylcarnitine in DD-CKD patients has been related to cardiac complications, impaired functional capacities, symptomatic intradialytic hypotension, and erythropoietin-resistant anemia." (PMID 36232995, 2022). "Blunted erythropoietin release has also been observed in more severe anemia, and kidney function appears to be an important factor here." (PMID 35334593, 2022). "While EPO levels are indeed increased, they are still lower than expected for the degree of anemia, suggesting blunted EPO production." (PMID 35204607, 2022). "CKD anaemia is largely derived from decreased erythropoietin (EPO) production due to the failure of kidney functions and iron deficiency." (PMID 35008998, 2022). "The kidney is the main source of erythropoietin (EPO), and progressive destruction of renal parenchyma decreases its availability, with this being one of the main causes of CKD-related anemia." (PMID 36432528, 2022). "These agents offer an oral alternative to parenteral erythropoietin (EPO) and can also induce red blood cell production in certain EPO-refractory conditions, such as anemia of chronic disease linked to high hepcidin levels." (PMID 36106637, 2022). "Inhibition of the prolyl-4-hydroxylase domain (PHD) enzymes, leading to the stabilization of hypoxia-inducible factor (HIF) α as well as to the stimulation of erythropoietin (Epo) synthesis, is the functional mechanism of the new anti-anemia drug roxadustat." (PMID 35203399, 2022). "Subjects with anemia had higher EPO, iFGF23, CRP, and phosphate and lower eGFR, while we were not able to show statistical difference regarding PTH, D vitamin, and calcium levels." (PMID 35739404, 2022).